PCDHGC4 (protocadherin gamma subfamily C, 4)
Description:
Potential calcium-dependent cell-adhesion protein. May be involved in the establishment and maintenance of specific neuronal connections in the brain.
Synonyms: PCDH-gamma-C4; NEDGS
Tractability: Antibody: UniProt places it where antibodies can reach, with medium confidence; UniProt predicts a signal peptide or a membrane-spanning region; its Gene Ontology location is reachable by antibodies, with medium confidence.
Gene: Protein-coding gene on chromosome 5 (141,484,997 to 141,512,975, forward strand). Ensembl gene ENSG00000242419.
Subcellular location: Cell membrane
Subcellular location (Human Protein Atlas): Plasma membrane; Vesicles; Cytosol; Nucleoplasm
Gene Ontology:
Molecular function: cell adhesion molecule binding; calcium ion binding
Biological process: cell adhesion; synapse organization; homophilic cell-cell adhesion; nervous system development
Cellular component: plasma membrane; membrane
Genetic constraint (gnomAD): Loss-of-function variants: 15 observed, 63.6 expected, observed/expected ratio (o/e) 0.24, 90% interval 0.16 to 0.36. The upper end of that interval is the gene's LOEUF score, 0.36, which puts it in group 1 of 6, group 1 being the genes least tolerant of losing a copy. Missense variants: 1,016 observed, 1,262.8 expected, observed/expected ratio (o/e) 0.8, 90% interval 0.76 to 0.85. Synonymous variants: 434 observed, 515.77 expected, observed/expected ratio (o/e) 0.84, 90% interval 0.78 to 0.91.
Homologues: Orthologues: mouse Pcdhgc4 (98% identical). Paralogues in human: PCDHGC5 (53% identical), PCDHGC3 (47% identical), PCDHGA4 (46% identical), PCDHGA5 (46% identical), PCDHGA10 (46% identical), PCDHGA11 (46% identical), PCDHGA12 (45% identical), PCDHGA6 (45% identical), PCDHGA1 (45% identical), PCDHGA3 (45% identical), PCDHGA8 (45% identical), PCDHGA2 (44% identical), and 49 more.
Diseases named in the same sentence as PCDHGC4 in open-access papers:
PCDHGC4 is named in the same sentence as 9 diseases in open-access papers, as found by Europe PMC text mining. Sharing a sentence is not in itself a finding about the gene and the disease. The quoted sentences say what the papers report.
microcephaly (3 papers, 2021 to 2024). A congenital or acquired developmental disorder in which the circumference of the head is smaller than normal for the person's age and sex. "PCDHGC4 variants have been linked to a neurodevelopmental disorder characterized by microcephaly, seizures, and intellectual disability." (PMID 38645146, 2024). "In all affected individuals who presented with a neurodevelopmental syndrome with progressive microcephaly, seizures, and intellectual disability we identified biallelic disease-causing variants in Protocadherin-gamma-C4 (PCDHGC4)." (PMID 34244665, 2021). "In the present study, we provide strong genetic evidence that biallelic nonsense and missense variants in PCDHGC4 cause a distinct neurodevelopmental phenotype comprising progressive microcephaly, short stature, intellectual disability, seizures, and joint anomalies." (PMID 34244665, 2021).
liver cancer (1 paper, 2022). An epithelial or non-epithelial malignant neoplasm that arises from the liver. "Several studies have shown that PCDH genes are also involved in liver cancer development, including PCDH10, PCDH17, PCDH19, PCDH20, PCDHGC4, and PCDHGC5." (PMID 36230503, 2022).
tumor (2 papers, 2015 to 2019). "Differently, PCDHGC4 and PCDHGC5 were commonly hypermethylated in a large variety of tumours." (PMID 31288858, 2019).
PCDHGC4 also shares sentences with these, for which no sentence is quoted: Intellectual disability (2 papers); neurodevelopmental disorder (2); cancer (1); developmental delay (1); Neurodevelopmental delay (1); Seizure (1).